NPIPA1 (nuclear pore complex interacting protein family member A1)
Synonyms: NPIP; morpheus; NPIPA
Tractability: No criterion of Open Targets' tractability assessment is met for any kind of drug.
Gene: Protein-coding gene on chromosome 16 (14,922,802 to 14,952,060, forward strand). Ensembl gene ENSG00000183426.
Subcellular location: Nucleus, nuclear pore complex; Nucleus membrane
Subcellular location (Human Protein Atlas): Nucleoplasm
Gene Ontology:
Cellular component: nuclear membrane; nuclear pore
Genetic constraint (gnomAD): Loss-of-function variants: 0 observed, 4.91 expected, observed/expected ratio (o/e) 0, 90% interval 0 to 0.61. That is too few expected variants to judge how well the gene tolerates losing a copy. Missense variants: 22 observed, 82.88 expected, observed/expected ratio (o/e) 0.27, 90% interval 0.19 to 0.38. Synonymous variants: 7 observed, 24.69 expected, observed/expected ratio (o/e) 0.28, 90% interval 0.16 to 0.53.
Homologues: Paralogues in human: NPIPA6 (99% identical), NPIPA9 (99% identical), NPIPA7 (98% identical), NPIPA8 (98% identical), NPIPA3 (94% identical), NPIPA2 (94% identical), NPIPA5 (93% identical), NPIPB2 (72% identical), NPIPB4 (69% identical), NPIPB5 (69% identical), NPIPB12 (68% identical), NPIPB13 (68% identical), and 7 more.